Y_RNA (Y RNA )
Gene: Miscellaneous RNA gene on chromosome 5 (160,008,445 to 160,008,546, forward strand). Ensembl gene ENSG00000199398.
Homologues: Orthologues: chimpanzee Y_RNA (99% identical), macaque Y_RNA (94% identical). Paralogues in human: Y_RNA (90% identical), RNY3 (89% identical), RNY3P1 (89% identical), Y_RNA (89% identical), Y_RNA (88% identical), RNY3P14 (87% identical), Y_RNA (87% identical), Y_RNA (86% identical), Y_RNA (85% identical), RNY3P11 (84% identical), Y_RNA (84% identical), Y_RNA (83% identical), and 96 more.